MN1 (MN1 proto-oncogene, transcriptional regulator)
Diseases named in the same sentence as MN1 in open-access papers (continued):
Sharing a sentence is not in itself a finding about the gene and the disease.
meningioma (18 papers, 2012 to 2025). A generally slow growing tumor attached to the dura mater. "Previous studies reported that MN1 gene was a candidate genetic risk factor for sporadic meningioma cases." (PMID 23691496, 2013). "MN1 is implicated as a tumor suppressor in meningioma and an oncoprotein in acute myeloid leukemia." (PMID 35440587, 2022). "Furthermore, MN1 was initially found to cause gene rearrangement by chromosomal balanced translocation, which plays an important role in the pathogenesis of meningioma and myeloproliferative diseases." (PMID 35677036, 2022). "At diagnosis, high expression of the AML-associated genes BAALC (brain and acute leukemia, cytoplasmic) and MN1 (meningioma-1) were repeatedly linked to inferior outcomes in patients consolidated with chemotherapy while data for patients receiving HSCT remain limited." (PMID 32862286, 2020). "The MN1 gene encodes a transcription factor which may be involved in development of meningioma." (PMID 32886284, 2020). "The MN1 (Meningioma 1) gene is an important transcriptional co-regulatory factor that is initially discovered in meningiomas and has been confirmed to be involved in the occurrence and development of various malignant tumors in recent years." (PMID 41019085, 2025). "It should be noted that putative meningioma tumor suppressive meningioma 1 (MN1) in this module was differentially expressed between malignant and benign meningioma, indicating it can be used as a predictor of meningioma classification." (PMID 32983987, 2020). "While BAALC maps to chromosome band 8q22.3 and was initially identified in AML patients harboring a trisomy 8, MN1 is located on chromosome 22q12.3 and a transcription coactivator firstly described in meningioma pathogenesis." (PMID 32862286, 2020). "Analysis for fusion transcripts in these latter samples showed a consistent apparent inter-chromosomal translocation between MN1 (meningioma disrupted in balanced translocation 1, 22q12.1) and BEND2 (BEN domain containing 2, Xp22.13)." (PMID 29348602, 2018). "Resent research indicates that MN1 (a putative meningioma tumour suppressor) was found to be differently expressed in malignant and benign meningiomas." (PMID 27429002, 2016). "Meanwhile, MN1 inactivation could induce meningioma formation." (PMID 27677590, 2016). "In WHO°II meningiomas reduced expression of LEPR and MN1 resulted in a significantly shorter PFS, while in WHO°III meningiomas this was the case for a higher expression levels of PTTG1 and UBE2C." (PMID 26894859, 2016). "In accordance with our findings, the remaining four top genes were previously found to be either upregulated (UBE2C and PRC1) or downregulated (LEPR and MN1) in WHO grade II and III meningiomas." (PMID 26894859, 2016). "While mutations in MN1 have previously been implicated in acute myeloid leukemia (AML) and meningioma, it has not been reported in STS." (PMID 36464833, 2023).
neuroepithelial tumor (18 papers, 2017 to 2025). "Patient 28 with a high-grade neuroepithelial tumor with MN1 alteration (HGNET-MN1-altered) and a TSC2 mutation was treated with everolimus with SD over twelve months." (PMID 35864412, 2022). "In contrast, important CpG sites in the PWWP domain containing 3A, DNA repair factor (PWWP3A, commonly known as MUM1) gene locus for the prediction of MC high-grade neuroepithelial tumor with MN1 alteration (HGNET-MN1) were located in the gene body." (PMID 40481322, 2025). "EET MN1-BEND2 was first identified as a subset of pediatric CNS tumors belonging to a methylation class defined as high-grade neuroepithelial tumors with MN1 alteration (HGNET-MN1)." (PMID 36604386, 2023). "The first MN1 fusions located in the CNS were described in an entity named central nervous system high-grade neuroepithelial tumor with MN1 alterations (CNS HGNET–MN1)." (PMID 35169893, 2022). "MN1 alteration characterizes a new class of central nervous system high-grade neuroepithelial tumors that have recently been identified based on epigenetic investigations and profiles of a large cohort of tumor samples." (PMID 35204463, 2022). "By DNA methylation profiling, tumors with MN1 or RELA rearrangement clustered with high-grade neuroepithelial tumor with MN1 alteration (HGNET-MN1) and RELA-fusion ependymoma, respectively." (PMID 30876455, 2019). "They rather encompass several low- to higher-grade glial tumors including neuroepithelial tumors with MN1 rearrangement, PXA-like tumors, RELA ependymomas, and possibly yet uncharacterized lesions." (PMID 30876455, 2019). "A further case, a compact and necrotic tumor with perivascular radiating arrangements, displayed a methylation classifier score strongly indicative of a high-grade neuroepithelial tumor with MN1 alteration (CNS HGNET-MN1, methylation classifier score = 0.713)." (PMID 29763623, 2018). "Neuroepithelial tumors (NET) with PATZ1 fusions (NET-PATZ1) have been isolated by a distinct DNA methylation profile and are characterized by recurrent fusions of PATZ1 in association with EWSR1 or MN1 genes." (PMID 35115049, 2022). "Therefore, I will henceforth refer to it as neuroepithelial tumors with MN1 alteration (NET-MN1)." (PMID 36604386, 2023). "Next, CNS high-grade neuroepithelial tumor with genetic alterations in either BCOR (HGNET-BCOR), FOXR1 (HGNET-FOXR1) or MN1 (HGNET-MN1) are newly described subtypes all characterized by distinct molecular alterations." (PMID 33260839, 2020). "One group, termed high-grade neuroepithelial tumor with MN1 alteration (HGNET-MN1), showed recurrent rearrangements of the MN1 gene, located at 22q12.3-qter." (PMID 30876455, 2019). "There was no overlap with the recently described high-grade neuroepithelial tumors with MN1 fusions, which are characterized by MN1-BEND2 and MN1-CXXC5." (PMID 39409964, 2024).
acute myeloid leukemia (17 papers, 2012 to 2025). Acute myeloid leukemia (AML) is a group of neoplasms arising from precursor cells committed to the myeloid cell-line differentiation. "Meningioma 1 (MN1) is an independent prognostic marker for normal karyotype acute myeloid leukemia (AML), with high expression linked to all-trans retinoic acid resistance and poor survival." (PMID 28960191, 2017). "In analysis of the expression of the meningioma 1 (MN1) gene and MN1-associated microRNA in Chinese adult de novo acute myeloid leukemia (AML) patients, Xiang found that increased expression of MN1 was associated with reduced miR-20a expression and increased miR-181b expression." (PMID 27179712, 2016). "MN1 causes acute myeloid leukemia when overexpressed in mouse HSPC." (PMID 23626719, 2013). "High MN1 expression in gliomas is linked to longer progression-free survival (PFS), while elevated MN1 levels in acute myeloid leukemia (AML) are associated with shorter PFS." (PMID 40308577, 2025). "Furthermore, studies show that KAT8 influences acute myeloid leukemia (AML) differentiation by suppressing MN1 (meningioma 1) expression, a gene associated with rapid leukemia onset when overexpressed." (PMID 38790268, 2024). "MN1 alterations have also been described in acute myeloid leukemia (AML) with a potential prognostic impact." (PMID 39409964, 2024). "MN1 overexpression has been linked to shorter overall (OS) and disease-free survival (DFS) of patients diagnosed with acute myeloid leukemia with normal cytogenetics." (PMID 33540760, 2021). "The transcriptional co-factor meningioma 1 (MN1) gene is highly expressed, and its upregulation is inversely correlated with miR-20a and miR-181b transcripts in acute myeloid leukemia (AML) patients." (PMID 32138313, 2020). "The MN1 oncogene is deregulated in human acute myeloid leukemia and its overexpression induces proliferation and represses myeloid differentiation of primitive human and mouse hematopoietic cells, leading to myeloid leukemia in mouse models." (PMID 23626719, 2013). "Translocations of Meningioma-1 (MN1) occur in a subset of acute myeloid leukemias (AML) and result in high expression of MN1, either as a full-length protein, or as a fusion protein that includes most of the N-terminus of MN1." (PMID 33542482, 2021). "Transduction of MN1 into progenitor-enriched BMCs led to their transformation into acute myeloid leukemia cells (AML cells)." (PMID 30700727, 2019). "The transcriptional co-activator MN1 confers a worse prognosis for patients with acute myeloid leukemia (AML) when highly expressed; however, the mechanisms involved are unknown." (PMID 22905229, 2012). "The CXXC5 gene is evolutionarily conserved, with a length of 35.5 kbp, and localized on human chromosome 5q31.2, where it is close to regions frequently deleted in patients with acute myeloid leukemia (AML) or myelodysplastic syndrome (MDS) and found to be an abnormal fusion partner with MN1." (PMID 39806388, 2025).
glioma (15 papers, 2016 to 2025). A benign or malignant brain and spinal cord tumor that arises from glial cells (astrocytes, oligodendrocytes, ependymal cells). "In primary central nervous system tumors, changes in the MN1 gene are uncommon and typically associated with MN1 translocations." (PMID 39963393, 2025). "Expanding the molecular characterization of MN1-altered gliomas could increase diagnostic accuracy and inform targeted therapeutic approaches." (PMID 40628732, 2025). "The presence of BRAFV600E mutations in some ABs and MN1 rearrangements in others raises questions as to whether AB represents a distinct entity, or a histologic pattern exhibited by multiple glial tumor types." (PMID 30876455, 2019). "In addition, some subtypes of pediatric and young adult high‐grade gliomas, including those with MN1 alterations, MYCN amplifications, and H3‐3A G34 mutations, may be histologically indistinguishable from CNS embryonal tumors." (PMID 35763016, 2022). "Three genes (HOXA7, SLC2A4RG and MN1) were selected to establish a three-gene signature in lower grade gliomas." (PMID 27677590, 2016). "However, the high expression of MN1 in low-grade gliomas actually predicts a better prognosis, and this tissue-specific difference suggests that the regulatory network of MN1 is highly complex." (PMID 41019085, 2025). "So far, it is unknown with respect to the relationship between the expression of MN1 at the transcriptome level and the prognosis of glioma." (PMID 35677036, 2022). "In this study, a three-gene signature (MN1, HOXA7, and SLC2A4RG) could divide lower grade glioma patients into low-and high-risk groups, with longer OS obtained in the former group." (PMID 27677590, 2016). "The 8 low-grade gliomas harbored alterations in BRAF, KRAS, FGFR3, and MN1." (PMID 40980447, 2025).
myeloid leukemia (5 papers, 2012 to 2019). A clonal proliferation of myeloid cells and their precursors in the bone marrow, peripheral blood, and spleen. "We reasoned that comparison of the transcriptomes of cells expressing full length MN1 or a non-leukemogenic MN1-mutant could provide a more refined insight into the genetic program causing MN1-induced myeloid leukemia." (PMID 23626719, 2013). "Using these novel model systems, we show that overexpression of MN1 in the hematopoietic lineages results in spontaneous development of myeloid leukemia in vivo." (PMID 31332244, 2019). "As proof of concept, we confirm that MN1 overexpression in the hematopoietic lineage is sufficient to drive myeloid leukemia." (PMID 31332244, 2019). "We found that integrity of the regions between amino acids 12 to 458 and 1119 to 1273 are required for MN1’s in vivo transforming activity, generating myeloid leukemia with some mutants also producing T-cell lympho-leukemia and megakaryocytic leukemia." (PMID 23626719, 2013). "Overexpression of MN1 induces myeloid leukemia and blocks erythroid differentiation." (PMID 24367366, 2013). "Therefore, these 2038 MN1-specific transcripts are potentially involved in MN1-induced myeloid leukemia, whereas the 1110 overlapping transcripts between MN1-cells and Δ12–228-cells may play a role in MN1-induced enhanced myeloproliferation and impaired differentiation of murine bone marrow cells." (PMID 23626719, 2013).
osteosarcoma (5 papers, 2023 to 2025). A usually aggressive malignant bone-forming mesenchymal neoplasm, predominantly affecting adolescents and young adults. "MN1 also acts as an oncogene in osteosarcoma, where its stability and translation are regulated by specific m6A modifications, contributing to tumor progression and chemotherapy resistance." (PMID 40308577, 2025). "MN1 enhances mRNA stability through m6A methylation modification mediated by METTL14, promoting tumor progression and chemotherapy resistance in osteosarcoma." (PMID 41019085, 2025). "In osteosarcoma, METTL14, highly expressed, prevents the degradation and enhances the translational efficiency of MN1 mRNA through the m6A‐IGF2BP2 axis, contributing to tumorigenicity and conferring all‐trans‐retinoic acid resistance." (PMID 39021049, 2024). "In osteosarcoma, METTL14 facilitated tumor progression by upregulating the m6A modification of MN1 mRNA." (PMID 39054337, 2024). "In addition, METTL14-mediated MN1 methylation raises the stability and translation of MN1 transcript through the IGF2BP2-dependent pathway, prompting all-trans-retinoic acid resistance and progression in osteosarcoma." (PMID 37280679, 2023).
CEBALID syndrome (4 papers, 2022 to 2024). "Monoallelic LoF coding mutations in MN1 cause CEBALID syndrome, a disorder affecting multiple organ systems." (PMID 39333082, 2024). "A subset of individuals with coding variants in MN1 are reported to have CEBALID syndrome with DRS100." (PMID 39333082, 2024). "The MN1 gene is necessary for palate development, and mutations in this gene result in a genetic condition called CEBALID syndrome." (PMID 38956580, 2024). "The published cases with CEBALID syndrome carried de novo C-terminal MN1 truncation variants that were suggested to act in a dominant-negative or gain-of-function manner." (PMID 34974531, 2022). "The MN1 gene was only recently associated with CEBALID syndrome (Craniofacial defects, dysmorphic ears, structural brain abnormalities, expressive language delay, and impaired intellectual development; OMIM #618774)." (PMID 34974531, 2022). "To date, 27 variants in the MN1 gene have been reported to cause CEBALID syndrome." (PMID 38956580, 2024). "The loss-of-function mutation of MN1 may induce CEBALID syndrome, which is manifested as neurodevelopmental impairments and facial deformities." (PMID 35677036, 2022).
brain tumor (3 papers, 2022 to 2025). "Research has identified a co-regulatory gene of MN1 on chromosome 22, which is implicated in mutations associated with human brain tumours." (PMID 39963393, 2025). "Further analysis of data acquired from the CCLE database revealed stronger cell proliferation and invasion abilities in cell lines of brain tumors with the silencing of MN1 expression." (PMID 35677036, 2022). "Recent reports have identified a handful of pediatric brain tumors displaying a fusion of the PATZ1 gene with either MN1 or EWSR1 as a partner." (PMID 35204463, 2022). "Specifically, KIF18A, as a risk factor, could significantly reduce the proliferation of most tumor cell lines (including brain tumor cell lines), while MN1, as a protective factor, could enhance the proliferation of most tumor cell lines (including brain tumor cell lines)." (PMID 35677036, 2022).
myeloproliferative disease (3 papers, 2014 to 2022). "The minimal portion of MN1 with biologic function was MN1Δ3-7, corresponding to the 317 amino acids at the N-terminus, which induced a myeloproliferative disease with long latency and 50% penetrance." (PMID 25401736, 2014). "We chose the MN1 oncogene to enhance the engraftment of CMML cells as MN1 enhances self-renewal and blocks differentiation of CD34+ cord blood cells in vitro and induces a myeloproliferative disease, but not AML, in vivo." (PMID 32576961, 2020).
astrocytoma (2 papers, 2024 to 2025). "In astrocytoma and other nervous system tumors, MN1 gene rearrangements (such as MN1-BEND2 and MN1-CXXC5) drive tumor occurrence via activating the PDGFRα signaling pathway." (PMID 41019085, 2025).
craniosynostosis (2 papers, 2015 to 2025). Craniosynostosis is defined as the premature fusion of one or more cranial sutures leading to secondary distortion of skull shape resulting in skull deformities with a variable presentation. "Moreover, mutations in the Cyp26(a1,b1,c1) genes manifest in human patients by calvarial mineralization defects, craniosynostosis, hypertelorism, and learning disabilities, clinical features within the neuro-skeletal systems resembling the phenotype of patients with MN1 deletions." (PMID 40424121, 2025). "MN1 is the gene that was validated only in 1 out of 2 samples by qRT-PCR that would not preclude its importance in craniosynostosis in some cases." (PMID 25987937, 2015).
developmental delay (2 papers, 2021 to 2024). "We reported on a patient who carried the MN1 variant in the C-terminal region with mild developmental delay and normal brain magnetic resonance image (MRI)." (PMID 34975401, 2021). "The disruption of the MN1 gene’s normal function likely plays a role in the manifestation of the various symptoms, including developmental delay, language difficulties, dysmorphic facial features, skeletal deformities, hyperphagia, hyperactivity, and severe aggressive behavior." (PMID 38956580, 2024). "In our study, we first presented a MN1 C-terminal frameshift deletion variant that caused mild global developmental delay, cleft palate, and dysmorphic facial features but with no hearing loss or brain magnetic resonance image (MRI) abnormalities." (PMID 34975401, 2021).
Ewing sarcoma (2 papers, 2017 to 2021). A small round cell tumor that lacks morphologic, immunohistochemical, and electron microscopic evidence of neuroectodermal differentiation. "MN1 alteration is one of the molecular hallmarks of the recently described HGNET-MN1 tumor subentity, while EWSR1 has long been known to be involved in Ewing sarcoma, even though the exact factors underlying its oncogenicity remain to be fully understood." (PMID 34417833, 2021).
Intellectual disability (2 papers, 2024 to 2025). "Several genes, including HCFC1 and MN1, have been reported in the literature, causing intellectual disability of various intensities." (PMID 38956580, 2024).
lymphoma (2 papers, 2013 to 2019). A malignant (clonal) proliferation of B- lymphocytes or T- lymphocytes which involves the lymph nodes, bone marrow and/or extranodal sites. "In addition, we show that T-cell specific activation of MN1 in combination with loss of Pten increases tumour penetrance and stimulates the formation of Lyl1+ murine T-cell lymphoblastic leukemias or lymphomas (T-ALL/T-LBL)." (PMID 31332244, 2019).
T-cell lymphoma (2 papers, 2013 to 2014). "It is currently unclear if some of the deletion mutants of MN1 directly generate T-cell lymphoma, given that 4 out of 8 cases were GFP+ and the remaining 4 cases GFP−." (PMID 23626719, 2013).
acute leukemia (1 paper, 2020). A clonal (malignant) hematopoietic disorder with an acute onset, affecting the bone marrow and the peripheral blood. "The AML-associated genes BAALC (brain and acute leukemia, cytoplasmatic) and MN1 (meningioma-1) have been shown to be physiologically expressed at high levels in myeloid progenitor cells and downregulated during maturation and to promote leukemogenesis through blockage of myeloid differentiation." (PMID 32862286, 2020).
anemia (1 paper, 2014). A reduction in the number of red blood cells, the amount of hemoglobin, and/or the volume of packed red blood cells. "The MN1 mutations that enhanced engraftment and proliferation in vivo also induced high WBC counts, anemia, and thrombocytopenia." (PMID 25401736, 2014).